KYNU (kynureninase)
Description:
Catalyzes the cleavage of L-kynurenine (L-Kyn) and L-3-hydroxykynurenine (L-3OHKyn) into anthranilic acid (AA) and 3-hydroxyanthranilic acid (3-OHAA), respectively. Has a preference for the L-3-hydroxy form. Also has cysteine-conjugate-beta-lyase activity.
Synonyms: KYNUU; VCRL2
Tractability: Small molecule: a structure with a bound ligand is known; a high-quality ligand is known; it has a binding pocket of medium quality; it belongs to a druggable protein family. PROTAC: ubiquitination databases record sites on it; its protein half-life has been measured; a small molecule that binds it is known.
Target class: Enzyme; Hydrolase
Gene: Protein-coding gene on chromosome 2 (142,877,613 to 143,055,833, forward strand). Ensembl gene ENSG00000115919.
Subcellular location: Cytoplasm, cytosol
Subcellular location (Human Protein Atlas): Cytosol; Nucleoplasm
Pathways (Reactome):
Metabolism: Tryptophan catabolism
Gene Ontology:
Molecular function: kynureninase activity; protein homodimerization activity; pyridoxal phosphate binding
Biological process: L-tryptophan catabolic process; NAD+ biosynthetic process; quinolinate biosynthetic process; response to type II interferon; response to vitamin B6; 'de novo' NAD+ biosynthetic process from L-tryptophan
Cellular component: cytosol; mitochondrion; cytoplasm
Genetic constraint (gnomAD): Loss-of-function variants: 24 observed, 24.74 expected, observed/expected ratio (o/e) 0.97, 90% interval 0.7 to 1.36. The upper end of that interval is the gene's LOEUF score, 1.36, which puts it in group 5 of 6, group 1 being the genes least tolerant of losing a copy. Missense variants: 324 observed, 329.44 expected, observed/expected ratio (o/e) 0.98, 90% interval 0.9 to 1.08. Synonymous variants: 107 observed, 122.97 expected, observed/expected ratio (o/e) 0.87, 90% interval 0.74 to 1.02.
Gene-disease validity (ClinGen):
ClinGen rates the evidence that KYNU causes each of these diseases.
vertebral, cardiac, renal, and limb defects syndrome 2 (autosomal recessive): Definitive.
Homologues: Orthologues: chimpanzee KYNU (99% identical), macaque KYNU (98% identical), dog KYNU (87% identical), pig KYNU (87% identical), guinea pig KYNU (85% identical), rat Kynu (85% identical), mouse Kynu (83% identical), rabbit KYNU (80% identical), tropical clawed frog kynu (64% identical), zebrafish kynu (60% identical), Caenorhabditis elegans kynu-1 (42% identical).
Diseases named in the same sentence as KYNU in open-access papers:
KYNU is named in the same sentence as 63 diseases in open-access papers, as found by Europe PMC text mining. Sharing a sentence is not in itself a finding about the gene and the disease. The quoted sentences say what the papers report.
breast carcinoma (9 papers, 2015 to 2023). "Among the key genes, ASPN, DOCK2, THY1 and KYNU were found to be associated with breast cancer based on NCBI Entrez database." (PMID 32867782, 2020). "The administration of a pharmacologically optimized kynureninase had substantial therapeutic effects when combined with approved checkpoint inhibitors or with a cancer vaccine for the treatment of 4T1 breast carcinoma, melanoma or CT26 colon carcinoma tumors." (PMID 35173722, 2022). "In melanoma, colon cancer CT26 and breast cancer 4T1 models, combination of engineered kynureninase with ICI exhibited significant tumor growth inhibition and survival benefit." (PMID 35173722, 2022). "Hence, we examined the xenobiotic metabolism-associated genes (PYCR1, KYNU, CFB, HMOX1 and HES6) expressed in both breast cancer cells and in normal mammary epithelial cells." (PMID 37845207, 2023). "Kynureninase (KYNU), a tryptophan metabolism hydrolase, contributes to the production of NAD+cofactors via the kynurenine pathway, and KYNU is implicated in the formation and spread of breast cancers." (PMID 36588537, 2022). "KMO and KYNU inhibitors may therefore be considered as potential options for the treatment of breast cancer and cutaneous squamous cell carcinoma." (PMID 34201791, 2021). "KYNU, CTSD and PMP22 are known to be up‐regulated in advanced metastatic cancers and correlate with poor prognosis whereas LAMB1 encodes a laminin‐1 protein shown to have reduced expression in breast cancer." (PMID 25241147, 2015). "In addition, MTT assay results showed that highly expressed KYNU could inhibit the proliferation and migration of breast cancer cells, suggesting that KYNU is a tumor suppressor gene in breast cancer; this may be related to differences in tumor species and pathological patterns." (PMID 37742026, 2023).
melanoma (7 papers, 2020 to 2025). A malignant, usually aggressive tumor composed of atypical, neoplastic melanocytes. "Notably, high KYNU expression was linked to better outcomes in two melanoma subtypes: uveal melanoma (UVM) and metastatic skin cutaneous melanoma lesions (SKCM.met)." (PMID 40427178, 2025). "Of note, the expression of KYNU (encoding kynureninase, a key enzyme in the kynurenine metabolic pathway involved in immune response) has been correlated with CD4 T cell state in the melanoma microenvironment." (PMID 38334658, 2024). "Collecting the GSE152699 and GSE152722 datasets, we found that KYNU expression decreased after treatment with the anti-BAF drug vemurafenib in melanoma cell lines." (PMID 35893303, 2022). "In syngeneic mice model of melanoma, depletion of Kyn in both plasma and tumor by Kyn-degrading enzymes kynureninase reduced Kyn levels in IDO1, TDO2 and IDO1/TDO2-expressing cancer cells and augmented effector T cells in tumor, without impact on Trp levels." (PMID 35173722, 2022). "KYNU was overexpressed in keratinocytes (HaCaT and HEKα) and melanoma cells (A375 and H1205-lu)." (PMID 35893303, 2022). "Expression of KMO is not detected in healthy skin, as previously reported or melanoma tumors; while the protein expression of KYNU is lower compared to CCBL1 and CCBL2 both in healthy skin and melanoma tumors." (PMID 32117720, 2020).
psoriasis (7 papers, 2009 to 2025). An autoimmune condition characterized by red, well-delineated plaques with silvery scales that are usually on the extensor surfaces and scalp. "Several genes in the psoriasis classifier, KYNU (up), MUC7 and CLDN8 (down), were part of the Etanercept “molecular scar” previously reported by our group." (PMID 22957057, 2012). "Furthermore, processed amyloid β induces transcription of kynureninase, which we found to be strongly upregulated in psoriasis in vivo, as well as in psoriasis-derived cells in vitro, and which can elicit an inflammatory skin reaction in vivo." (PMID 19399181, 2009). "Studies on kynurenine pathway in psoriasis are very limited but demonstrate upregulation of KP in psoriasis patients and an increased activity of two enzymes—indoleamine 2,3-dioxygenase (IDO) and L-kynureninase (KYNU)—in psoriatic lesions." (PMID 40243933, 2025). "The authors discovered four DEPs, namely kynureninase/KYNU, lectin galactoside-binding soluble 3-binding protein/LG3BP, and tryptase β2/TPSB2, and carbonic anhydrase 6/CA6, in the sera of psoriasis patients." (PMID 35327421, 2022).
glioma (6 papers, 2014 to 2026). A benign or malignant brain and spinal cord tumor that arises from glial cells (astrocytes, oligodendrocytes, ependymal cells). "In this regard, kynureninase or L-kynurenine hydrolase (KYNU) is a KP enzyme located in 2q22.2 gene that has been poorly studied in glioma." (PMID 36986469, 2023). "Overall survival (OS) analysis from TCGA and CGGA datasets in low-grade gliomas showed that KYNU expression correlated with poor prognosis (p < 0.0001); that is, the higher the expression of KYNU, the lower the probability of survival." (PMID 36986469, 2023). "Considering these previous studies which indicated that KYNU could be a key KP enzyme in cancer, we decided to analyze the expression and the biological function of KYNU in gliomas, using the data available in the Chinese Glioma Genome Atlas (CGGA) and The Cancer Genome Atlas (TCGA)." (PMID 36986469, 2023). "Six genes of these essential TrMGs, including MAOB, HSD17B10, KYNU, AOX1, and OGDH, were determined as hazardous factors for glioma patients, and other two genes (CYP2E1 and ALDH2) were identified as protective factors." (PMID 36386216, 2022). "Additionally, KYNU expression was negatively correlated with overall survival in both LGG and GBM, indicating that KYNU might be an effective marker to predict the prognosis of glioma patients, regardless of race." (PMID 36986469, 2023).
schizophrenia (5 papers, 2015 to 2024). A major psychotic disorder characterized by abnormalities in the perception or expression of reality. "Such an intervention might be especially effective in the elderly, considering the aging-associated decline of rat liver kynureninase activity, and in male schizophrenia patients, given the lower plasma AA levels in males compared to females." (PMID 39769034, 2024). "KMO impairment in schizophrenia-specific brain areas (e.g., Brodmann area 10) increases the availability of Kyn as a substrate for both kynureninase and KAT." (PMID 39769034, 2024). "Therefore, clinical data suggest only the partial activation of kynureninase activity in individuals with schizophrenia and AD." (PMID 39769034, 2024). "Notably, of the three enzymes that use Kyn as a substrate, KAT and kynureninase are unsaturated enzymes that are able to utilize the increased availability of Kyn resulting from KMO deficiency (e.g., in the brains of individuals with schizophrenia)." (PMID 39769034, 2024). "The inhibition of KAT by estrogens might contribute to female-specific AA elevation, considering that Kyn is a common substrate for both kynureninase and KAT, while KMO activity is downregulated in individuals with schizophrenia." (PMID 39769034, 2024). "Considering that KMO is already impaired in individuals with schizophrenia, one may suggest that the inhibition of KAT would increase Kyn availability as a substrate for kynureninase, consequently leading to a robust increase in AA formation." (PMID 39769034, 2024). "In schizophrenia discovered the lack of kynureninase in astrocytes that can be one of the reasons for increasing the level of KYNA in schizophrenia." (PMID 32116664, 2019).
colon carcinoma (4 papers, 2022 to 2024). "Beside its direct tumoricidal effect in mice bearing CT26 colon carcinoma, kynureninase treatment induced accumulation of effector CD8 T cells within the tumor nest, as well as higher level of IFN-γ in the TME." (PMID 35173722, 2022). "Moreover, the combination of kynureninase with anti-PD1 was more effective than the latter with epacadostat in colon cancer mice model." (PMID 35173722, 2022).
lung adenocarcinoma (4 papers, 2019 to 2025). A carcinoma that arises from the lung and is characterized by the presence of malignant glandular epithelial cells. "We previously reported a novel mechanism of NRF2 tumoral immune suppression through selective upregulation of the tryptophan-metabolizing enzyme kynureninase (KYNU) in lung adenocarcinoma." (PMID 36765792, 2023). "Previously, we reported a novel mechanism of NRF2 tumoral immune suppression through the selective upregulation of the tryptophan-metabolizing enzyme kynureninase (KYNU) in lung adenocarcinoma." (PMID 36765792, 2023). "Recently, we reported an unrecognized role of NRF2 activation through loss-of-function KEAP1 mutations in upregulating the tryptophan-metabolizing enzyme kynureninase (KYNU) in lung adenocarcinoma (LUAD)." (PMID 36765792, 2023). "Specifically, proteomic profiles of 47 lung adenocarcinoma (LUAD) cell lines (11 KEAP1 mutant and 36 KEAP1 wild-type) revealed the tryptophan-kynurenine enzyme kynureninase (KYNU) as a top overexpressed protein associated with activated NRF2." (PMID 35626147, 2022). "Proteomic profiles of 47 lung adenocarcinoma (LUAD) cell lines (11 KEAP1 mutant and 36 KEAP1 wild-type) revealed the tryptophan-kynurenine enzyme kynureninase (KYNU) as a top overexpressed protein associated with activated NRF2." (PMID 35626147, 2022). "We analyzed gene expression from 3114 patients across 23 lung adenocarcinoma (LUAD) datasets and identified KYNU as a top bimodally distributed gene with high expression associated with poor prognosis." (PMID 40427178, 2025).
gastric cancer (3 papers, 2020 to 2025). A primary or metastatic malignant neoplasm involving the stomach. "KYNU overexpression is also correlated with adverse clinical phenotypes of gastric cancers." (PMID 40616124, 2025). "The overexpression of KYNU was also confirmed correlated with poor prognosis in gastric cancer." (PMID 36386216, 2022). "The functions of ZNF823, ZFP69B, SP6, KYNU, KIF21B, and TTF2 have not been reported in gastric cancer." (PMID 32848739, 2020).
astrocytoma (2 papers, 2022 to 2023). "Considering that KYNU is overexpressed in astrocytoma and has a prognostic value in OS, the next step was to analyze the association of KYNU with immunosuppression." (PMID 36986469, 2023).
cervical cancer (2 papers, 2024). A primary or metastatic malignant neoplasm involving the cervix. "However, to the best of our knowledge, nadB and kynU genes have never been reported to be associated with cervical cancer, indicating that further studies are needed to investigate the potential action and underlying mechanisms of these genes on cervical cancer." (PMID 39450338, 2024).
glioblastoma (2 papers, 2023 to 2025). The most malignant astrocytic tumor (WHO grade IV). "Using a genetically-engineered mouse model designed to inhibit production of QA, we identify kynureninase as a promising therapeutic target to revert the potent immune suppressive microenvironment in glioblastoma." (PMID 36927729, 2023).
Obesity (2 papers, 2022). Accumulation of substantial excess body fat. "In addition to KMO, the enzymes KYNU and KAT may also play a role in the relationship between the kynurenine pathway, obesity and T2D." (PMID 34996930, 2022).
cervical adenocarcinoma (1 paper, 2023). An adenocarcinoma arising from the cervical epithelium. "We previously identified the differentially expressed kynureninase (KYNU) mRNA in cervical adenocarcinoma cells (HeLa) and cervical adenocarcinoma cisplatin resistance cells (HeLa/DDP) using gene chips." (PMID 37742026, 2023). "Considering the difficulties of clinical treatment, we previously investigated the differential expression of kynureninase (KYNU) mRNA in cervical adenocarcinoma cells (HeLa/DDP) and cervical adenocarcinoma cisplatin-resistant cells (HeLa/DDP) using gene chips." (PMID 37742026, 2023).
cutaneous squamous cell carcinoma (1 paper, 2021). "Furthermore, some authors observed that the expression levels of KMO and KYNU are potently upregulated in the course of HER2-enriched and triple-negative breast cancer subtypes, as well as cutaneous squamous cell carcinoma." (PMID 34201791, 2021).
Insulin resistance (1 paper, 2024). Increased resistance towards insulin, that is, diminished effectiveness of insulin in reducing blood glucose levels. "MSR1, KYNU, and RBKS, but not SMPD1, were associated with metabolic and liver dysfunction markers, while SCARA5, TNFRSF12A, SMOC2, but not GDF-8, were associated with insulin resistance markers." (PMID 39407757, 2024).
ischemia (1 paper, 2022). A hypoperfusion of the BLOOD through an organ or tissue caused by a PATHOLOGIC CONSTRICTION or obstruction of its BLOOD VESSELS, or an absence of BLOOD CIRCULATION. "We noticed that 3‐hydroxyanthranilic acid (3‐HAA) produced by catalytic hydrolysis of kynurenine through kynureninase and kynurenine 3‐monooxygenase, was the second most downregulated hit during ischemia, while KYNA was the most upregulated metabolite." (PMID 36310151, 2022).
leiomyoma (1 paper, 2022). A well-circumscribed benign smooth muscle neoplasm characterized by the presence of spindle cells with cigar-shaped nuclei, interlacing fascicles, and a whorled pattern. "Recent reports from our laboratory revealed dysregulation of tryptophan catabolism in leiomyomas, with tumors of African American women expressing more TDO2 (tryptophan 2,3-dioxygenase) mRNA but lower levels of KYNU (L-Kynurenine hydrolase) mRNA as compared to Caucasian women." (PMID 35641855, 2022).
leukemia (1 paper, 2025). A malignant (clonal) hematologic disorder, involving hematopoietic stem cells and characterized by the presence of primitive or atypical myeloid or lymphoid cells in the bone marrow and the blood. "Similarly, in a human leukemia monocytic cell line (THP1) exposed to OSPW [25% v/v OSPW in cell culture medium], the upregulation of kynureninase (KYNU)—an enzyme in the kynurenine pathway—was observed, further linking NA exposure to altered tryptophan metabolism." (PMID 40407525, 2025).
pellagra (1 paper, 2019). "Also, the presenceof high levels of leucine in maize and sorghum aggravates the pellagra byactivation of TDO and ACMSD and inhibition of kynureninase and QPRT." (PMID 31105983, 2019). "Even with marginal niacin, but adequate Trp, intake,clinical or subclinical pellagra can be induced by drugs interfering withone or more enzymes of the KP, e.g. by TDO inhibition by some antibioticsand antiviral drug or kynureninase inhibition by hydrazine compounds oroestrogens." (PMID 31105983, 2019).
prostate carcinoma (1 paper, 2025). A carcinoma that arises from epithelial cells of the prostate gland. "And anthranilate, derived from the catabolism of kynurenine by kynureninase, was upregulated in correlation with the prostate‐specific antigen (PSA) level of prostate cancer patients and was supported to promote tumor immune infiltration." (PMID 40937009, 2025).
type 2 diabetes mellitus (1 paper, 2018). A type of diabetes mellitus that is characterized by insulin resistance or desensitization and increased blood glucose levels. "In addition, small subsets of genes encoding for regulatory factors and enzymatic processes that have been implicated in the pathogenesis of type 2 diabetes mellitus (T2DM) were profiled, including interferon regulatory factors (IRF), indoleamine 2,3-dioxygenase (IDO1) and kynureninase (KYNU)." (PMID 29746559, 2018).